LINC01224 (long independently transcribed non-coding RNA 1224)
Gene: Long non-coding RNA gene on chromosome 19 (23,399,092 to 23,416,186, reverse strand). Ensembl gene ENSG00000269416.
Diseases named in the same sentence as LINC01224 in open-access papers:
LINC01224 is named in the same sentence as 13 diseases in open-access papers, as found by Europe PMC text mining. Sharing a sentence is not in itself a finding about the gene and the disease. The quoted sentences say what the papers report.
colorectal cancer (3 papers, 2019 to 2025). A primary or metastatic malignant neoplasm that affects the colon or rectum. "TRPM2-AS interacts with the transcription factor ELK1 in gastric cancer, while LINC01224 interacts with YY1 in colorectal cancer, both of which influence cell cycle progression and stress responses." (PMID 40149330, 2025). "LINC01224 performs a consistent role in tumours, and current studies have revealed that it promotes progression in different types of tumours, i.e., gastric cancer, colorectal cancer, and lung cancer." (PMID 36844873, 2023).
liver cancer (2 papers, 2021 to 2023). An epithelial or non-epithelial malignant neoplasm that arises from the liver. "LINC01224 is a long-chain noncoding RNA, and current studies have shown that its expression is elevated in liver cancer and epithelial ovarian cancer and promotes tumor development." (PMID 33747079, 2021).
colon cancer (1 paper, 2022). "Therefore, interference with the expression of LINC01224 can inhibit the proliferation of colon cancer cells and induce cell cycle arrest in G0-G1 phase." (PMID 35433686, 2022).
squamous cell carcinoma (1 paper, 2024). A carcinoma arising from squamous epithelial cells. "However, besides S100A16, miR-6884-5p was reported to regulate l lncRNA LINC01224 as competitive endogenous RNA (ceRNA), and miR-6884–5p/Dishevelled segment polarity protein 3 (DVL3) axis also activated Wnt/β-catenin signaling pathway in squamous cell carcinoma." (PMID 38271114, 2024).
tumor (7 papers, 2021 to 2023). "The expression of IGF2BP3 at the mRNA and protein levels was attenuated by knockdown of linc01224, which indicated that downregulation of linc01224 inhibited tumor-promoting activity in HSCC by repressing IGF2BP3 protein synthesis." (PMID 37859812, 2023). "In summary, our research is the first to provide evidence that linc01224 acts as a novel tumor promoter through the miR-485-5p/IGF2BP3 axis in HSCC." (PMID 37859812, 2023). "Tumor growth curves and tumor weight assessment demonstrated that linc01224 knockdown significantly suppressed tumor growth in mice (P < 0.05)." (PMID 37859812, 2023). "The qRT-PCR results revealed significantly higher linc01224 expression in HSCC tissues compared to matched non-tumor tissues, as well as in FaDu cells." (PMID 37859812, 2023). "We confirmed that lower expression of linc01224 was detected in tumor tissues derived from linc01224 knockdown cells than control cells (P < 0.05)." (PMID 37859812, 2023). "A total of six lncRNAs, including AC099850.4, NRAV, AL031985.3, PRRT3-AS1, AL365203.2, and LINC01224, were highly expressed in tumor tissues, based on TCGA cohort analysis." (PMID 35845962, 2022). "We found that LINC01224 knockdown decreased xenograft tumor growth, indicating the anti-CRC role of LINC01224 knockdown in vivo." (PMID 34535152, 2021). "This analysis revealed that miR-485-5p has known tumor suppressor roles, its interaction with linc01224 may be important for understanding linc01224's molecular functions in FaDu cells." (PMID 37859812, 2023). "Growing evidence has shown that linc01224 plays a vital role in tumor progression." (PMID 37859812, 2023). "Moreover, LINC01224 promotes carcinogenesis and tumor development through serving as endogenous sponge for microRNAs (miRNA), including miRNA (miR)-2467." (PMID 34535152, 2021). "Furthermore, LINC01224 and MYO6 abundances were markedly higher and miR-485-5p was lower in the tumor tissues with sh-LINC01224#1 transfection." (PMID 34535152, 2021). "MiR-485-5p is suggested as a target for LINC01224 in epithelial ovarian cancer, and miR-485-5p could function as an important biomarker for CRC; furthermore, the tumor-suppressive role of miR-485-5p has also been discovered in CRC cells via affecting functional genes." (PMID 34535152, 2021). "Consistent with our previous experimental data using ten pairs of HSCC tumor tissues and adjacent nonneoplastic tissues by transcriptome sequencing, the expression of linc01224 was upregulated in FaDu cells, which may mean that linc01224 can participate in the pathogenesis of HSCC." (PMID 37859812, 2023).
cancer (5 papers, 2019 to 2023). A tumor composed of atypical neoplastic, often pleomorphic cells that invade other tissues. "It has been reported that LINC01224 is highly expressed in epithelial ovarian cancer and can promote the development of the cancer through miR-485-5p–mediated PAK4." (PMID 35433686, 2022). "LINC01224 can specifically upregulate the anti-apoptotic protein CHEK1 to influence the cancer cells." (PMID 34901153, 2021). "So far, no studies have reported any association between LINC00377, LINC00536, LINC01224, and LINC02037, and cancer." (PMID 31850229, 2019). "In addition, linc01224 promotes cancer proliferation by sponging miR-485-5p to upregulate PAK4 in epithelial ovarian cancer." (PMID 37859812, 2023). "Similarly, in this study, we found that the expression of linc01224, a cancer-promoting gene, was markedly enhanced in HSCC tissues by RNA sequencing." (PMID 37859812, 2023).
LINC01224 also shares sentences with these, for which no sentence is quoted: breast carcinoma (3 papers); endometrial cancer (2); gastric cancer (2); hepatocellular carcinoma (2); epithelial ovarian cancer (1); intraductal papillary mucinous neoplasms (1); lung carcinoma (1).